TSLP (thymic stromal lymphopoietin)
Diseases named in the same sentence as TSLP in open-access papers (continued):
Sharing a sentence is not in itself a finding about the gene and the disease.
Sepsis (9 papers, 2018 to 2025). Sepsis is defined as life-threatening organ dysfunction caused by a dysregulated host response to infection. "Collectively, our findings indicate that TSLP exerts a protective effect against sepsis-associated acute lung injury by reducing lung tissue damage and suppressing the secretion of inflammatory cytokines." (PMID 40486522, 2025). "This controversy surrounding endogenous TSLP’s role in lung inflammation has thus far limited our understanding of its impact on sepsis associated ARDS." (PMID 40486522, 2025). "Collectively, our findings highlight the crucial role of TSLP in immune regulation of sepsis-associated ARDS and demonstrate its clinical potential clinical value as both a predictive biomarker and therapeutic target." (PMID 40486522, 2025). "To investigate the role of TSLP in sepsis associated lung injury, we administered exogenous recombinant TSLP to wild-type mice, followed by lipopolysaccharide (LPS) challenge." (PMID 40486522, 2025). "We further explored a potential role of TSLP underlying pathogenesis of sepsis by injecting recombinant TSLP into septic mice (TSLP plus LPS-injected mice)." (PMID 31480519, 2019). "Given these functions, we hypothesized that pre-existing type 2 immune response cytokines, such as TSLP, may confer benefits in the context of sepsis-associated ARDS." (PMID 40486522, 2025). "We think that additional studies in this regard are imperative to establish whether patients receiving anti-TSLP therapy for the treatment of asthmatic or allergic disorders may be at higher risk of developing ARDS induced by sepsis, injury, or other causes." (PMID 32103153, 2020). "The TSLP levels were elevated in sepsis-associated AKI in both humans and rodent models." (PMID 32974364, 2020). "We performed the diagnostic test evaluation to evaluate whether TSLP levels predict mortality in patients with sepsis." (PMID 31628890, 2019). "TSLP deficiency lowered liver damage and inflammatory cytokine levels in mice with sepsis." (PMID 31480519, 2019). "We propose that the cutoff value of serum levels of TSLP could be used for risk assessment in the patients with sepsis with HNR and HL according to diagnostic test evaluation and may have potential value in the management of sepsis." (PMID 31628890, 2019). "Thus, additional investigation is urgently needed to understand the roles and mechanisms underlying induction of TSLP during sepsis." (PMID 31480519, 2019). "To assess whether TSLP contributes to the development of systemic inflammatory reaction during sepsis, we analyzed dynamic changes of inflammatory cytokine levels in TSLP-deficient mice." (PMID 31480519, 2019). "In the current study, we show that IL-25, IL-33, and TSLP expression increased in response to systemic inflammation caused by experimental peritonitis, and sepsis induces expansion of ILC2 in the lungs consistent with the changes in the expression of IL-25, IL-33, and TSLP." (PMID 29511181, 2018). "Therefore, TSLP may serve as a potential biomarker for the evaluation of the mortality risk in patients with sepsis with HNR and HL." (PMID 31628890, 2019). "Next, we investigated whether TSLP is also associated with organ dysfunction during sepsis." (PMID 31480519, 2019). "In the context of sepsis-induced liver injury and liver I/R injury, the hepatoprotective effects of TSLP have been confirmed through the activation of the PI3K/Akt pathway." (PMID 40486522, 2025). "Overall, our study underscores the crucial role of TSLP in sepsis-associated ARDS and provides valuable insights supporting TSLP as a potential beneficial predictor." (PMID 40486522, 2025). "We provide an overview of the current literature on the effects of IL-10, TGF-β and TSLP in sepsis and trauma and suggest therapeutic approaches for their modulation." (PMID 33717127, 2021). "Inhibition of TSLP, a TH2-inducing cytokine, with siRNA also resulted in lowering the sepsis-associated organ dysfunction and inflammatory cytokine levels." (PMID 32974364, 2020).
Sepsis (continued). "We recently found that patients with sepsis-induced acute respiratory distress syndrome (ARDS) exhibited increased plasma TSLP levels." (PMID 32103153, 2020). "Our study revealed the correlation between the levels of TSLP and prognosis in patients with sepsis." (PMID 31628890, 2019). "In this study, we observed that TSLP levels are higher in serum or organ tissues of both mice and humans with sepsis, which functions to induce an inflammatory reaction." (PMID 31480519, 2019). "Establishing TSLP inhibition as a novel sepsis therapy will require a careful assessment of its potential suppressive effects on infectious complications or host defense experimentally and clinically in the future." (PMID 31480519, 2019). "In this study, we investigated a regulatory mechanism of TSLP in sepsis using LPS-stimulated macrophages and an LPS-induced sepsis model." (PMID 31480519, 2019). "In the first study, the administration of a neutralizing antibody to TSLP in mice with sepsis resulted in decreased mortality and weakened the host immune response." (PMID 31628890, 2019). "In a cecal ligation and puncture (CLP) model which is a sepsis experimental model, TSLP levels were elevated up to about 70 pg/mL in serum or 200 pg/mL in plasma." (PMID 31480519, 2019). "We revealed the inflamed phenotype of immune cells in patients with sepsis with high levels of TSLP." (PMID 31628890, 2019). "The protein TSLP acts as an inflammatory cytokine and exerts specific effects on circulating immune cells from patients with sepsis with high TSLP levels." (PMID 31628890, 2019). "First, considering that this study is only a preliminary observational human study, the further mechanisms involved in the influence of TSLP on severe bacterial infection and sepsis." (PMID 31628890, 2019). "Previous studies about the interrelationship between TSLP and sepsis have revealed the elevated levels of TSLP in a colorectal ligation and puncture animal model." (PMID 31628890, 2019). "In summary, this study provides evidence that TSLP is produced via TLR4 signaling in macrophages during sepsis." (PMID 31480519, 2019). "Taken together, these findings suggest a novel mechanism in that TSLP regulates the development of sepsis." (PMID 31480519, 2019). "In this study, we used the ELISA to measure serum levels of TSLP in patients with sepsis, and used flow cytometry and ELISA to evaluate the proinflammatory phenotype of circulating immune cells." (PMID 31628890, 2019). "TSLP serves as a classical proinflammatory cytokine that has potential effects on patients with sepsis with severe SIRS." (PMID 31628890, 2019). "Recently, we observed increased plasma TSLP levels in sepsis-induced ARDS patients." (PMID 32103153, 2020). "The TSLP level significantly increased in serum of patients with sepsis (p < 0.05)." (PMID 31480519, 2019). "However, TSLP was controversially reported to exert antimicrobial activities, improve survival, and reduce inflammation in mice with sepsis." (PMID 31480519, 2019). "However, no clinical investigation has explored the effect and potential value of TSLP in patients with sepsis." (PMID 31628890, 2019). "Studies are warranted to evaluate whether the serum levels of TSLP are increased in patients with sepsis or if higher TSLP levels predict improved prognosis." (PMID 31628890, 2019). "Nutlin-3a significantly reduced TSLP levels in liver and lung of mice with sepsis (p < 0.05)." (PMID 31480519, 2019). "We first measured the TSLP level in serum of human patients with sepsis." (PMID 31480519, 2019). "Taken together, the findings suggest that TSLP may be closely linked to a synergistic effect on IL-6 and AST levels during sepsis." (PMID 31480519, 2019). "To evaluate the effect of TSLP on the function of neutrophils in patients with sepsis, we performed flow cytometry analysis and explored the functional changes in neutrophils in all sepsis regardless of whether these patients suffered from HNR and HL." (PMID 31628890, 2019).
Sepsis (continued). "We next investigated whether TSLP is involved in sepsis in a TLR4-dependent manner and thus focused on biological consequences of TSLP induced by LPS or E. coli in macrophages." (PMID 31480519, 2019). "However, the effect of TSLP in sepsis mice was opposite in two studies on a cecal ligation and puncture (CLP) mouse model." (PMID 31628890, 2019). "The elevated TSLP level during sepsis might lead to recruitment of inflammatory cells via ICAM-1 and MIP2." (PMID 31480519, 2019). "Thus, based on the present results, cisplatin can be considered a good candidate as a useful therapeutic option for patients with sepsis by downregulation of TSLP." (PMID 31480519, 2019). "This suggests that TSLP produced during sepsis increases IL-6 level, which may induce, at least in part, the changes in AST, ALT, and BUN levels." (PMID 31480519, 2019). "Thus, we revealed that an increase of TSLP is shown in not only the CLP-induced sepsis model but also the LPS- or E. coli-induced sepsis model." (PMID 31480519, 2019). "Therefore, the present findings demonstrate that TSLP can serve as a new target for the development of new drugs for treatment of sepsis." (PMID 31480519, 2019). "In the final series of this study, we sought to determine whether pharmacological inhibition of TSLP level could attenuate a septic response using cisplatin, which is a chemotherapeutic agent against tumor and sepsis." (PMID 31480519, 2019). "Our findings suggest that the serum levels of TSLP may be suitable as a biomarker for prediction of prognosis in a subgroup of patients with sepsis who are exhibiting hyperleukocytosis and a high neutrophil ratio." (PMID 31628890, 2019). "At the same time, the serum IL-6 and TNF-α levels which are early biomarkers for sepsis also reached a maximum at around 4 h and 2 h after the injection, respectively (p < 0.05), indicating that TSLP may be an early biomarker for sepsis." (PMID 31480519, 2019). "We found that TSLP levels were elevated in serum of patients and mice with sepsis." (PMID 31480519, 2019). "Thus, TSLP may exert adverse effects on the clinical outcomes in patients with sepsis with an intense immune response, which may lead to secondary systemic inflammatory response syndrome and secondary multiple organ failure." (PMID 31628890, 2019). "Thus, we investigated a role and regulatory mechanism of TSLP during sepsis." (PMID 31480519, 2019). "Thus, this study provides evidence that a high TSLP level may lead to organ dysfunction during sepsis, specifically increasing IL-6 and AST levels." (PMID 31480519, 2019). "Therefore, the TSLP‐induced antimicrobial effect dependent on neutrophils may fail to work in the case of other bacterial strains that participate in sepsis." (PMID 31628890, 2019). "Therefore, we now suggest that TSLP may contribute to organ dysfunction, which is required for sepsis development, affecting inflammatory cell responses." (PMID 31480519, 2019). "Therefore, since TSLP regulation could be of therapeutic value for sepsis treatment, understanding the role of TSLP would assist in discovering new targets for sepsis." (PMID 31480519, 2019). "However, the function of TSLP during sepsis is poorly understood." (PMID 31480519, 2019). "We found IL-24, CXCL1, TSLP and IL-8 were significantly different between the NEC and sepsis groups." (PMID 36806964, 2023). "We have further demonstrated that TSLP levels decrease in LPS-stimulated macrophages and mice with sepsis by nutlin-3a, indicating that MDM2 is important in regulating TSLP." (PMID 31480519, 2019). "Up to now, there is no research on the role of TSLP in the development of NEC, and we found TSLP level was significantly different between the NEC and sepsis, which suggests that TSLP may plays an important role in the pathophysiology of NEC." (PMID 36806964, 2023).
Sepsis (continued). "Therefore, the antibacterial effects of TSLP attributed to the production of reactive oxygen species in neutrophils from healthy individuals observed in in vitro experiments may disappear because of the functional defects in neutrophils from patients with sepsis." (PMID 31628890, 2019). "Altogether, the present results show that TSLP exacerbates septic inflammation via the MDM2 signaling pathway, suggesting that TSLP may be a potential target for the treatment of sepsis." (PMID 31480519, 2019). "Previous studies have reported conflicting effects of TSLP on sepsis in mice, and the effect of TSLP on sepsis in humans has not been investigated." (PMID 31628890, 2019). "In this study, we demonstrate elevated levels of TSLP in patients with sepsis and reveal the negative correlation between serum levels of TSLP in patients with sepsis with a high ratio of neutrophils and mortality." (PMID 31628890, 2019). "We recently reported that TSLP levels were increased in sepsis-induced ARDS4 patients, but the small number of patients tested did not allow us to statistically establish whether TSLP levels in these patients associated with clinical outcomes of the disease." (PMID 32103153, 2020). "Furthermore, we have demonstrated that, by using a lower concentration (100 μg/kg) of cisplatin, cisplatin reveals critical pharmacological effects by reducing TSLP levels without cytotoxicity in macrophages and mice during sepsis." (PMID 31480519, 2019).
acute lymphoblastic leukemia (8 papers, 2014 to 2025). Leukemia with an acute onset, characterized by the presence of lymphoblasts in the bone marrow and the peripheral blood. "Genetic rearrangements and mutations in the TSLP gene were detected in lymphoblastic leukemia." (PMID 31023965, 2019). "In T‐cell acute lymphoblastic leukemia (T‐ALL) patients, Stat5 phosphorylation was induced by TSLP, although CRLF2 protein was localized intracellularly." (PMID 33890726, 2021). "In leukemia, particularly acute lymphoblastic leukemia (ALL), the importance of TSLP is being increasingly recognized." (PMID 40787610, 2025). "Thymic stromal lymphopoietin (TSLP) is a biological agent similar to IL-7, which could play an important role in hematopoietic cell maturation and pediatric acute lymphoblastic leukemia stimulation." (PMID 34987176, 2022).
bronchiolitis (8 papers, 2017 to 2025). Inflammation of the bronchioles characterized by swelling of the bronchioles and mucus accumulation. "In contrast to TSLP, the nasal detection of periostin at admission for bronchiolitis was associated, in our series, with a more favourable respiratory outcome." (PMID 36694181, 2023). "Children hospitalized for bronchiolitis between October/2013 and July/2017, currently aged 4 years, included in a previous study to investigate the nasal airway secretion of TSLP and periostin during bronchiolitis, were included." (PMID 36694181, 2023). "Measurable nasal levels of TSLP were detected at admission for bronchiolitis in 27 (11%) cases and periostin in 156 (63%)." (PMID 36694181, 2023). "Our study found that compared with the control group, the levels of IL-17RB, TSLP, and IL-33 in the bronchiolitis group were significantly increased." (PMID 33514798, 2021). "The bronchiolitis group serum IL-5, IL-9, IL-13, IL-33, TSLP protein levels were higher than the normal control group." (PMID 33514798, 2021). "The mRNA expression levels of TSLP in the peripheral blood of the bronchiolitis group were greater than control group (16.98 ± 2.12 vs 15.07 ± 2.25, P < 0.05)." (PMID 33514798, 2021). "Identification of TSLP within samples collected from RSV-infected patients demonstrates its potential as a target for mitigation of RSV-induced bronchiolitis in humans." (PMID 32397226, 2020). "This study showed a correlation between increased levels of TSLP with hRSV bronchiolitis and coinfections with rhinovirus, as well as with severe disease and intensive care unit (ICU) admission." (PMID 31214165, 2019). "Our findings, in a recent study conducted in hospitalized infants with bronchiolitis and in healthy controls, showed that nasal TSLP and IL-33 are detected more frequently in viral coinfections than in single infections." (PMID 29206851, 2017). "Additionally, it has been reported that hospitalized infants with viral bronchiolitis have detectable levels of nasal IL-13, IL-33, and thymic stromal lymphopoietin (TSLP)." (PMID 29250560, 2017). "Therefore, IL-17RB, TSLP, IL-33 may participate in the development of bronchiolitis through ILC2s cells." (PMID 33514798, 2021). "Importantly, TSLP levels were upregulated in nasopharyngeal aspirates (NPAs) collected at time of admission of hospitalized infants with viral bronchiolitis, 70% of which were hospitalized due to RSV infection, compared to samples collected from healthy infants at their primary care appointments." (PMID 32397226, 2020). "There is growing evidence that TSLP and periostin are elicited in the upper airways of infants with RSV and HRV bronchiolitis, and increased TSLP levels are related to more severe disease and intensive care unit (ICU) admission." (PMID 36694181, 2023). "It is worth noting that no patient with bronchiolitis but with negative viral detection had detectable levels of nasal TSLP or IL-33, suggesting that the release of these proteins may be mediated by respiratory viruses." (PMID 29206851, 2017).
inflammatory skin disease (8 papers, 2016 to 2024). Inflammatory skin disorders covers a broad category that includes many conditions ranging in severity, from mild itching to grave medical health complications These disorders are common in people of all ages and races. "In inflammatory skin disorders and airway inflammation in in vivo models, TSLP was highly expressed." (PMID 36673369, 2023). "Within a month, the RAF1Δep animals developed an inflammatory skin disease characterized by K6 and ICAM1 expression in the epidermis, by the presence of activated dermal mast cells and by an increase in TSLP." (PMID 27431613, 2016). "When the epidermal barrier of the skin is damaged by physical or chemical stimuli, many cytokines (IL-1β, IL-6, TNF-α, IL-5, and TSLP) and chemokines (MCP-1, RNATES, TARC, MDC, CXCL8, and CXCL10) are expressed in stimulated keratinocytes to promote the progression of inflammatory skin diseases." (PMID 36670888, 2022).